APOB (apolipoprotein B)
Diseases named in the same sentence as APOB in open-access papers (continued):
Sharing a sentence is not in itself a finding about the gene and the disease.
diabetes (continued). "Accordingly, we hypothesise that increased uptake of LDL particles might injure adipocytes or islet cells or both, which might explain the strong positive association between apoB and the risk of diabetes that was observed in this study." (PMID 34729547, 2021). "Given the previous evidence that increased apolipoprotein B might be associated with progression of CKD in diabetes patients, apolipoprotein should be considered in future studies." (PMID 33307922, 2021). "Moreover, studies on Chinese Han population found that apoB/apoA1 was correlated with coronary heart disease risk factors such as diabetes mellitus and abnormal glucose tolerance." (PMID 32539722, 2020). "Epidemiological studies have also demonstrated that apolipoproteins and the apoB/apoA1 ratio represent potential risk factors for the development of type 2 diabetes mellitus (T2DM), insulin resistance, non-alcoholic fatty liver disease, metabolic syndrome, and cancer." (PMID 29312456, 2018). "A total of 31% individuals had high total cholesterol, 22% had low HDL-cholesterol, 31% had high LDL-cholesterol, 13% had high triglycerides, 18% had high apolipoprotein B, 6% had impaired fasting plasma glucose and 7% had HbA1c levels indicative of increased risk of diabetes." (PMID 29433574, 2018). "Since CVD risk in diabetes correlated with ex vivo apoB-depleted plasma cholesterol efflux, we tested the hypothesis that HDL-C may not always correlate with RCT capability." (PMID 30271349, 2018). "Small proportions of the family history effect were mediated by metabolic risk factors: 8.3% (95% CI: 5.8–11.7%) by the apoB pathway, 1.7% (95% CI: 0.2–3.4%) by apoA‐I, 8.5% (95% CI: 5.9–12.0%) by blood pressure, and 1.5% (95% CI: −0.8% to 3.8%) by diabetes mellitus." (PMID 28320750, 2017). "In the present study, a higher BMI was associated with increased risk for future RA, even when adjusting for smoking, ApoB/ApoA1 ratio, diabetes, hypertension and educational level, although, when stratifying for sex, the association of BMI ≥ 25.0 for future RA was restricted to men." (PMID 28666478, 2017). "However, the association between the ApoB/ApoA-I ratio and the risk of type 2 diabetes mellitus (T2DM) is still obscure." (PMID 28110289, 2017). "In pre-symptomatic women both smoking and an elevated ApoB/ApoA1 ratio were significantly more prevalent compared with matched controls, whereas in men smoking, BMI ≥ 25.0 and diabetes were significantly associated with increased risk of future development of RA." (PMID 28666478, 2017). "Therefore, a prospective and well-controlled study would be needed to elucidate the associations of ApoB/ApoA-I ratio with diabetes and pre-diabetes risk." (PMID 28110289, 2017). "Notably, we observed that ApoA1/HDL-C was independently associated with diabetes in both sexes, and the serum ApoB/LDL-C ratio was only consistently associated with the presence of diabetes in women." (PMID 24093822, 2013). "Furthermore, apoB was strongly associated with incident diabetes in FINRISK97 and had a borderline significant association (p = 0.053) in Health 2000." (PMID 20396381, 2010). "We used multivariable regression in a population-based cross-sectional study, undertaken from 1994 to 1996, of 2537 Hong Kong Chinese residents aged 25 to 74 years with clinical measurements of ischaemic heart disease (IHD) risk, including HDL-cholesterol, ApoB, diabetes and obesity." (PMID 17957253, 2007). "Moreover, at baseline, LDL/ATP-induced WAT IL-1β-secretion was associated in the direction of higher diabetes risk in subjects with high-apoB, associating negatively with 1st phase and total DI, IS, and WAT PPARG mRNA and positively with SREBP2 mRNA and android fat." (PMID 39511203, 2024).
diabetes (continued). "Nevertheless, monitoring lipoprotein levels aside from LDL-C may be critical in managing risk and minimizing morbidity and mortality due to CVD in specific subsets of patients such as those with diabetes, as discussed in Section 4 (How Do Pro-Atherosclerotic Risk Factors Affect ApoB levels)?" (PMID 34677405, 2021). "Although women with diabetes mellitus have an increased risk of cardiovascular morbidity and mortality compared with diabetic men, the present study revealed that women were undertreated and less likely to attain the recommended lipid and ApoB goals than their male counterparts." (PMID 29402296, 2018). "Accordingly, the American Diabetes Association and the American College of Cardiology Foundation recommend that therapy for patients with high cardiovascular disease risk should aim to lower ApoB concentrations to below 90 mg/dl in addition to reducing LDLc levels." (PMID 29695967, 2018). "Moreover, in women, the risk of diabetes and pre-diabetes in the top and middle tertiles of the ApoB/ApoA-I ratio were 3.65-fold (95% CI 1.69 to 6.10) and 2.19-fold (95% CI 1.38 to 2.84) higher than in the bottom tertile, respectively, after adjusting for potential confounding factors." (PMID 28110289, 2017). "In women, elevated ApoB/ApoA1 ratio (OR = 1.36 (1.03–1.80)) and smoking (OR = 1.82 (1.37–2.41)) were significantly associated with being pre-symptomatic for RA, whilst in men smoking (OR = 1.92 (1.26–2.92)) and diabetes (OR = 3.62 (95% CI 1.13–11.64)) were significant." (PMID 28666478, 2017). "Long‐term exposure to low LDL‐C levels due to APOB LoF variants has opposite consequences, reducing ASCVD risk but increasing CLD risk, especially in the presence of diabetes and obesity." (PMID 41549954, 2026). "Patients in the CRS group were older, had a higher proportion of diabetes mellitus, higher levels of TG, apo-B, and Scr, a higher ApoB/ApoA1 ratio, but lower levels of apo-A1 compared to the SHF group." (PMID 41908053, 2026). "In a univariate analysis, patients with ICAS had a higher prevalence of diabetes mellitus, smoking, and hyperlipidemia, as well as higher levels of ApoB and a higher ApoB/ApoA-I ratio, but lower levels of HDL-C and ApoA-I compared to those without ICAS." (PMID 42256577, 2026). "Statistically significant differences (p < 0.05) were observed between groups in age, cranial nerve involvement, gamma-glutamyl transferase (GGT), alkaline phosphatase, TC, LDL, HDL, ApoA, ApoB, sensory impairment, motor impairment, diabetes, and hypertension." (PMID 40822937, 2025). "Elevated GCF levels of oxLDL and apoB indicate enhanced vascular permeability and local oxidative modification, particularly in diabetes." (PMID 41465350, 2025). "The results revealed that ApoB was significantly associated with depression risk across multiple subgroups, including sex, BC, AF, arrhythmia, cancer, CHD, diabetes, stroke, pneumonia, CKD, TD, and OP (all P < 0.05)." (PMID 41458557, 2025). "Among individual attributes, the main effectsranked in descending order of influence were BMI, NE, PLT, WBC, hypertension,age, type 2 diabetes mellitus, TC, ApoB, smoking, alcohol consumption,rs2000813, Lp(a), and rs3813082." (PMID 40776945, 2025). "These factors included blood glucose levels, ALP, ALT, GGT, total cholesterol, HDL, triglycerides, ApoA1, ApoB, sex, age, BMI, the length of illness, initial age of disease manifestation, marital condition, presence of diabetes, and hypertension." (PMID 40810071, 2025). "In diabetes, LDL glycosylation increases with glucose levels, and AGE and Apolipoprotein B levels rise in diabetics." (PMID 40429748, 2025). "Destacamos como metas principais o LDL-c e, como coprimária, o não-HDL-c, além de enfatizar a importância da dosagem de ApoB, especialmente em pacientes com diabetes, devido à maior presença de partículas aterogênicas que contêm ApoB." (PMID 41379178, 2025).
diabetes (continued). "A large cohort-based study known as “INTERHEART” conducted across 52 countries identified several risk factors associated with MI, which include smoking, hypertension, abnormal lipid profile/blood lipoprotein (ApoB/ApoA1), and diabetes mellitus." (PMID 40270498, 2025). "Diabetes is associated with a specific dyslipidemic profile, characterized by higher TG levels, low HDL-C, high apolipoprotein-B levels, and smaller, denser LDL-C particles." (PMID 40565987, 2025). "Significant differences were observed in the abnormal-NCS group, including older age, longer diabetes duration, higher levels of fasting plasma glucose, HbA1c, and apolipoprotein B, along with lower eGFR, HDL-C, and Apo A-I levels." (PMID 40142241, 2025). "A recent study has demonstrated that apoB predicts the long-term prognosis for coronary atherosclerosis to a considerable extent in patients with diabetes, obesity, and MetS." (PMID 40598589, 2025). "The main effects of single attributes, ranked in descending order, areas follows: BMI, NE, PLT, WBC, hypertension, age, type 2 diabetes mellitus, TC,ApoB, smoking, alcohol consumption, rs2000813, Lp(a), andrs3813082." (PMID 40776945, 2025). "Modifiable risk factors relevant for CVD include arterial hypertension (HTN), smoking, diabetes mellitus (DM) and plasmatic lipids containing apolipoprotein B." (PMID 38541026, 2024). "The results depicted that theCC genotype in rs7257062 was an independent risk factor for CADafter adjusting gender, smoking history, diabetes, hypertension, TG, TC, HDL-C,LDL-C and ApoB." (PMID 39076552, 2024). "TG, TC, HDL-C, ApoA, LDL-C, and ApoB levels as well as the prevalence of diabetes were significantly greater in females than in males (P = 0.017, p = 0.016, P = 0.049, P = 0.002, P = 0.021, P = 0.022, and P = 0.045, respectively)." (PMID 39080710, 2024). "Multiple studies confirm that SHBG has a direct effect on metabolic health and diabetes through SHBG polymorphisms and apolipoprotein B." (PMID 38660513, 2024). "FSG: fasting serum glucose; LDL/HDL-C: high-density lipoprotein cholesterol/low-density lipoprotein cholesterol ratio; ApoB/ApoA: apolipoprotein A/apolipoprotein B ratio; DM: diabetes mellitus." (PMID 39081429, 2024). "LDL/HDL-C: high-density lipoprotein cholesterol/low-density lipoprotein cholesterol ratio; ApoB/ApoA: apolipoprotein A/apolipoprotein B ratio; DM: diabetes mellitus." (PMID 39081429, 2024). "Prior investigations have established a significant link between glycoprotein acetyls, apolipoprotein B, lipids, and the risk of CVD in individuals with psoriasis and those with diabetes." (PMID 39458547, 2024). "Epidemiological data confirmed that plasma apoB predicts the incidence of diabetes 3–21 years before its onset." (PMID 39511203, 2024). "Univariate logistic regression revealed that diabetes, previous stroke, heart rate, WBC, ALT, FBG, cTnT, and Fg were risk factors for the high GS, ApoA1/ApoB, and PCSK6 rs1531817 CA + AA genotypes were protective factors against the occurrence of high GS." (PMID 39039525, 2024). "In a study conducted among the Tallinn population aged 20–65, a higher PWV was observed in hypertensive men aged equal to or above 50 years, as well as in hypertensive women with diabetes and in apparently healthy women with increased apolipoprotein B." (PMID 37447671, 2023). "In line with our findings, epidemiological data emerging since 2007 confirmed that plasma apoB predicts the incidence of diabetes 3–21 years before its onset independently of traditional risk factors including adiposity and glycemia." (PMID 37914804, 2023). "Overall, this model, including age, gender, systolic blood pressure, diabetes, hip circumference, vitamin D, apolipoprotein-A, apolipoprotein-B, hypertension, and smoking, explained 22% of the variance in cIMT in the UK Biobank population." (PMID 37754787, 2023).
diabetes (continued). "The ApoB/ApoA-I ratio, as well as age, diabetes, and poor medication adherence, were independently associated with 1-year stroke recurrence." (PMID 38274879, 2023). "Elevated plasma numbers of atherogenic apoB-lipoproteins (apoB), mostly as low-density lipoproteins (LDL), predict diabetes risk by unclear mechanisms." (PMID 37914804, 2023). "The table shows 14 study variables, which are composed of Serum Klotho, ApoB, Gender, Age, Race, Education level, Ratio of family income to poverty, Hypertension, High cholesterol level, BMI, Diabetes, Drinking, Smoking, and Cancer." (PMID 37352065, 2023). "The stepwise model ended with these factors: age, gender, systolic blood pressure, diabetes, hip circumference, vitamin D, apolipoprotein-A, apolipoprotein-B, hypertension and smoking." (PMID 37754787, 2023). "S1PR5 expression was correlated with diabetes, heart rate, triglycerides, total cholesterol, low-density lipoprotein cholesterol, apolipoprotein B, and fasting blood glucose (P < 0.05)." (PMID 35837598, 2022). "Serum ApoB and TC levels were positively associated with arthritis after adjusting for sex, age, weight, BMI, disease duration, PASI and BSA score, diabetes, and hypertension." (PMID 34996506, 2022). "ApoB is the best marker to predict concomitant disease, which was positively correlated with diastolic blood pressure, the concomitant of diabetes and arthritis." (PMID 34996506, 2022). "There were significant differences in proportion of participants with hypertension and diabetes at Y25, with the highest of each in the high-apoB/high-TG groups." (PMID 35462864, 2022). "Alirocumab and evolocumab reduce LDL-C by about 60% in patients with diabetes and dyslipidemia, and also have a very positive effect on other lipid fractions in patients with diabetes: TG (− 15–30%), apolipoprotein B (− 35%) and Lp(a) (− 20–30%)." (PMID 36443827, 2022). "Atherogenic dyslipidemia (AD), characterized by increased concentrations of apolipoprotein B (ApoB)-containing particles, is often present in individuals with type 2 diabetes mellitus (T2DM)." (PMID 33941192, 2021). "In recent years, with the increasing number of patients with CHD who have comorbidities of hyperlipidemia and/or diabetes mellitus, the importance of apoB has been elevated." (PMID 34657601, 2021). "ε2ε3 carriers differed from ε3ε3 in having lower risk of IHD, lower SBP, pulse pressure and plasma apoB, and nominally lower HbA1c, but similar DBP and risk of diabetes." (PMID 33927215, 2021). "The influx of fatty acids into hepatocytes due to hyperinsulinemia in diabetes is more than the capacity of excretion of protein, such as apolipoprotein B of hepatocytes." (PMID 33598196, 2021). "The 2019 European Society of Cardiology (ESC) lipid guidelines already recommend using apolipoprotein B (apoB) as an evaluation marker in obese people or in the case of combined hyperlipidemia and/or diabetes." (PMID 34657601, 2021). "Higher apoB shortens lifespan, increases risks of heart disease and stroke, and in multivariable analyses that account for LDL cholesterol, increases risk of diabetes." (PMID 34729547, 2021). "In patients with RI or diabetes, a defect in the regulatory capacity of insulin on ApoB secretion has been demonstrated, leading to increased VLDL release." (PMID 33801107, 2021). "This study aimed to investigate the susceptibility of 8 polymorphisms in ApoB and PCSK9 genes to diabetic kidney disease (DKD) in Chinese patients with type 2 diabetes mellitus." (PMID 33889589, 2021). "In the present study, in addition to Pcsk9 levels, ApoB, creatine kinase, NT-proBnp, diabetes were also independent predictors of SYNTAX scores." (PMID 34044829, 2021). "Our findings implicate apoB in several major diseases, including heart disease, stroke, and diabetes." (PMID 34729547, 2021). "Our findings indicate that ApoB gene is a candidate gene for DKD in Chinese patients with type 2 diabetes mellitus." (PMID 33889589, 2021).
diabetes (continued). "Despite these limitations, our findings indicate that ApoB gene is a candidate gene for DKD in Chinese patients with type 2 diabetes mellitus." (PMID 33889589, 2021). "ε4ε4 carriers differed from ε3ε3 carriers in having higher risk of IHD, pulse pressure and plasma apoB, while having lower HbA1c, but similar SBP and diabetes risk." (PMID 33927215, 2021). "Viktorinova and colleagues found that the level of small dense LDL in persons with diabetes can be estimated based on the ratio of LDL/apoB such that there is an inverse relationship between these parameters." (PMID 34677405, 2021). "Abundant evidence has proven a higher predictive ability of the ApoB/ApoA1 ratio for CVDs, obesity, insulin resistance, and diabetes over conventional biomarkers." (PMID 32717783, 2020). "This interaction disappeared after additional adjustment for diabetes mellitus, ApoA-I, ApoB, ApoE, and Lp(a)." (PMID 32546151, 2020). "Results were essentially the same when models were concurrently adjusted for gender, age, apoB concentration, diabetes, past CVD history, CRP, and eGFR." (PMID 30813431, 2019). "The diabetes patients had greater waist circumference compared with the controls, as well as higher HbA1c and apolipoprotein B. At baseline they also had higher BMI, total cholesterol, LDL cholesterol and apolipoprotein A-I." (PMID 30359432, 2018). "The sdLDL-C levels in the hyper-TG/-apoB group were 50% higher in patients with diabetes and CAD than those in controls." (PMID 28125987, 2017). "The LDL-C/apoB ratios were significantly lower in patients with CAD or diabetes than those in healthy subjects, which was consistent with the difference in LDL size." (PMID 28125987, 2017). "We investigated the association between the LDL-C/apoB ratio and TG metabolism in coronary artery disease (CAD) patients with diabetes mellitus (DM)." (PMID 28969633, 2017). "The hyper-apoB/-TG group represented 92% of sdLDL-C Q4 and 0% of Q1 and Q2, indicating an increased discrimination between higher sdLDL-C levels in patients with diabetes compared with healthy subjects." (PMID 28125987, 2017). "Subjects with T2DM had much higher ApoB/ApoA-I ratios than those with pre-diabetes and NGT, accompanied by worse glucose and lipid profiles." (PMID 28110289, 2017). "Pearson's partial correlation and multivariable logistic analysis were used to evaluate the associations between ApoB/ApoA-I ratio and the risk of T2DM and pre-diabetes." (PMID 28110289, 2017). "Similar to patients with diabetes, a high prevalence of the hyper-apoB/-TG group was observed in patients with CAD who also had sdLDL-C levels that were 50% higher than those of the same group of healthy subjects." (PMID 28125987, 2017). "This study emphasizes the CV, diabetes, and liver disease risks in A-T patients evidenced by atherogenic lipid profile [higher values of Lp(a) and ApoB/Apo A-I], IR, and presence of hepatic steatosis in 64.7% of the patients." (PMID 28778179, 2017). "Among diabetes, hypertension, abdominal obesity and smoking, a family lipoprotein disorder such as a high level of serum apolipoprotein B (Apo B) or/and a lower level of serum apolipoprotein A-1 accounted for almost all the population attributable risk of AMI." (PMID 23631751, 2013). "In general, people with diabetes tend to have elevated concentrations of triglycerides and apolipoprotein B, low concentrations of high-density lipoprotein cholesterol, and an elevated number of small dense low-density lipoprotein cholesterol particles." (PMID 23360385, 2013).